WAC-AS1 (WAC antisense RNA 1)
Gene: Long non-coding RNA gene on chromosome 10 (28,519,917 to 28,533,066, reverse strand). Ensembl gene ENSG00000254635.
Diseases named in the same sentence as WAC-AS1 in open-access papers:
WAC-AS1 is named in the same sentence as 6 diseases in open-access papers, as found by Europe PMC text mining. Sharing a sentence is not in itself a finding about the gene and the disease. The quoted sentences say what the papers report.
hepatocellular carcinoma (2 papers, 2021 to 2023). A malignant tumor that arises from hepatocytes. "Recent studies have identified WAC-AS1 as a protective factor in glioma but a risk factor in hepatocellular carcinoma, which are in line with our findings." (PMID 37248547, 2023).
liver cancer (1 paper, 2021). An epithelial or non-epithelial malignant neoplasm that arises from the liver. "We analyzed the expression of WAC-AS1 in 50 normal liver tissue samples and 374 liver cancer tissue samples in the TCGA database and found that WAC-AS1 expression was significantly higher in liver cancer tissues than in normal tissues (P<0.001)." (PMID 34527595, 2021).
primary immunodeficiency (1 paper, 2023). "The GSEA results showed that the calcium signaling pathway, and the renin-angiotensin system were negatively related to WAC-AS1, and the cytosolic DNA sensing pathway, glycosylphosphatidylinositol GPI anchor biosynthesis, and primary immunodeficiency were positively linked to WAC-AS1 in SARC." (PMID 37248547, 2023).
tumor (3 papers, 2021 to 2023). "Taken together, our findings show WAC-AS1 is a tumor promoter and a key regulator of OS cell stemness and metastasis via a miR-5047/SOX2 axis." (PMID 37957698, 2023). "In order to confirm the expression of WAC-AS1 by online database analysis, we selected a multi-tumor tissue microarray and used in situ hybridization to detect the expression of WAC-AS1." (PMID 37248547, 2023).
cancer (2 papers, 2023). A tumor composed of atypical neoplastic, often pleomorphic cells that invade other tissues. "In TCGA, WAC-AS1 was upregulated in most types of cancer tissues compared with normal tissues." (PMID 37957698, 2023). "Moreover, WAC-AS1 increases tumorsphere formation and the expression of SOX2, a master regulator of cancer stemness and CSC self-renewal, while decreasing the chemo-sensitivity of OS cells, indicating that WAC-AS1 regulates the stemness of OS." (PMID 37957698, 2023). "Despite the significant correlations of WAC-AS1 with TMB and MSI, the correlation coefficients across all types of cancers were less than 0.5, suggesting that WAC-AS1 expression may not be used as an independent predictor for patients’ response to ICBs." (PMID 37248547, 2023).
WAC-AS1 also shares sentences with these, for which no sentence is quoted: glioma (1 paper).